IL10 (interleukin 10)
Diseases named in the same sentence as IL10 in open-access papers (continued):
Sharing a sentence is not in itself a finding about the gene and the disease.
rheumatic heart disease (3 papers, 2016 to 2025). An autoinflammatory condition following an infection with Group A Beta Hemolytic Streptococcus (GABHS), in which the heart is attacked by antibodies formed in reaction to a recent GABHS infection. "A case control study of single nucleotide polymorphisms and rheumatic heart disease in patients with rheumatic heart disease in the IL-10-1082G/A was collected." (PMID 29552315, 2018). "Among them, the correlation between IL-10-1082G/A polymorphism and rheumatic heart disease is one of the most important parts of the study." (PMID 29552315, 2018). "Abdallah study showed that the effect of IL-10 on the role of 1082G/A in patients with rheumatic heart disease is related to the single nucleotide polymorphisms (SNPs) in the gene promoter region." (PMID 29552315, 2018). "When AA is a recessive gene, the single nucleotide polymorphism of IL-10-1082G/A is associated with the presence of rheumatic heart disease." (PMID 29552315, 2018). "Systematic review of the association between single nucleotide polymorphism of IL-10-1082G/A locus and rheumatic heart disease." (PMID 29552315, 2018). "In conclusion, this study found that the polymorphism of IL-10-1082G/A gene may be related to the risk of rheumatic heart disease." (PMID 29552315, 2018). "The presence of chronic inflammation is evidenced by the presence of INF-γ, TNF-α, and IL-10 in biopsied valve tissue in patients with rheumatic heart disease." (PMID 27418982, 2016). "Similarly, our study demonstrated that DEX significantly lowered myocardial injury markers (cTnI and CK-MB) and inflammatory markers (IL-8, TNF-α), increasing IL-10 levels in patients undergoing valve replacement for rheumatic heart disease." (PMID 40951900, 2025). "The results showed that there was a certain correlation between the single nucleotide polymorphism of IL-10-1082G/A and rheumatic heart disease, but there was no systematic study to verify this conclusion." (PMID 29552315, 2018).
rhinoscleroma (3 papers, 2013 to 2018). A granulomatous disease caused by klebsiella rhinoscleromatis infection. "To evaluate the putative role of IL-10 in the pathogenesis of rhinoscleroma we challenged BALB/c IL-10-deficient mice with K. rhinoscleromatis and compared them to WT BALB/c mice." (PMID 23554169, 2013). "Their data showed that interleukin-10 is highly expressed upon infection with Klebsiella rhinoscleromatis and suggested an important role of this cytokine in the phenotypic maturation of Mikulicz cells and thereby in rhinoscleroma pathogenesis." (PMID 27293924, 2016). "Moreover, a detailed understanding of how IL-10 expression is regulated during rhinoscleroma may unravel new therapeutic strategies to modulate IL-10 production." (PMID 23554169, 2013). "Moreover, our data show that interleukin-10 (IL-10) is highly expressed upon infection with K. rhinoscleromatis and that it plays a crucial role in the phenotypic maturation of Mikulicz cells and thereby in rhinoscleroma pathogenesis." (PMID 23554169, 2013).
rosacea (3 papers, 2023 to 2025). A chronic erythematous skin disorder that affects the face. "Probiotics, such as certain strains of Lactobacillus, Bifidobacteria and Saccharomyces, can positively influence several immune mechanisms that are implicated in rosacea pathogenesis by increasing IL10 and reducing TNF-a, IL-17A." (PMID 40149947, 2025). "Research indicates elevated levels of proinflammatory cytokines such as IL-1a, along with reduced levels of anti-inflammatory cytokines such as IL-10 in the tears of rosacea patients with ocular symptoms." (PMID 39859986, 2025). "The expression of proinflammatory innate cytokines, including Th1 polarizing cytokines Il12b and Tnf; Th17/Th22 polarizing cytokines Il1b, Il23a, and Il6; and Il10 were significantly induced as compared with controls showing a similar expression profile as in rosacea." (PMID 36633910, 2023). "Among innate cytokines, we observed a significant increase in TNF, IL1B, IL8, IL12B, IL23A, and IL10 — but not IL36B — in rosacea skin lesions as compared with skin from healthy donors." (PMID 36633910, 2023).
shigellosis (3 papers, 2017 to 2021). Shigellosis is a bacterial infection leading to dysentery and is caused by Shigella, which are small, ubiquitous Gram-negative bacteria belonging to the enterobacteria family. "The p-values were significant (<0.05) for IL-1β, IL-10, IFN-γ and TNF-α, but IL-2 and IL-4 levels were insignificant in shigellosis patients’ sera." (PMID 28767653, 2017). "We earlier showed that IL-10 levels were not detectable in serum or stool of patients during acute and convalescent phases of shigellosis; however, expression of the cytokine in rectal tissue was prominent during both phases." (PMID 34374425, 2021).
tendinopathy (3 papers, 2019 to 2021). "In contrast, to prevent tendinopathy the high production of IL-17 by PBMCs is limited, especially when IL-6 and IL-10 production is up-regulated." (PMID 33233549, 2020). "The treatment also increased muscle levels of IL-10, and prevented the elevation of CD68+ macrophages in several tissues as well as task-induced tendinopathy, similar to other types of manual therapies, as discussed further below." (PMID 33952219, 2021).
teratocarcinoma (3 papers, 2007 to 2023). A germ cell tumor characterized by the presence of an embryonal carcinoma component and a teratoma component. "Furthermore, HERV-K particles produced by human teratocarcinoma cells were also found to induce the release of interleukin-10 (IL-10)." (PMID 37958549, 2023).
thyroid tumor (3 papers, 2010 to 2017). A benign or malignant neoplasm affecting the thyroid gland. "On the other hand, thyroid tumors, which frequently display mutation in ras, respond to an autocrine IL-10 signalization loop where tumor cells secrete and proliferate in response to IL-10." (PMID 20525400, 2010). "Furthermore, autocrine secretion of IL-10 promotes thyroid tumour cell progression and resistance to chemotherapy through the up-regulation of anti-apoptotic proteins." (PMID 28099146, 2017).
Tremor (3 papers, 2015 to 2024). An unintentional, oscillating to-and-fro muscle movement about a joint axis. "When early stage and late stage CSF cytokines were compared, IL-10 and IL-6 were up regulated in late stage patients and were associated with a reduction in tremors and cranioneuropathy." (PMID 26090964, 2015).
tuberculous meningitis (3 papers, 2008 to 2022). "Other studies have found genetic polymorphisms in host immune responses that are associated with EPTB, including Manose-Binding Protein and TB meningitis, Interleuken (IL)-1β/IL-1R, IL-10 and IFN-γ, and NRAMP1 and pleural TB." (PMID 18394166, 2008).
Urinary incontinence (3 papers, 2012 to 2025). Loss of the ability to control the urinary bladder leading to involuntary urination. "Therefore, maintaining physiological levels of both serotonin and IL-10 is crucial in women with GDM urinary incontinence." (PMID 38138954, 2023). "The reduced melatonin levels observed in this group of pregnant women correlated positively with IL-10 and inversely with TNF-α, reinforcing the possibility that urinary incontinence may result from a defective biological effect of melatonin." (PMID 41295285, 2025).
uveal melanoma (3 papers, 2015 to 2025). A melanoma derived from melanocytes of the uveal tract. "Next, we proceeded to explore the expression of the members of IL-10/IL-10R system, miR-15a, miR-185, and miR-211 in cutaneous and uveal melanoma samples as compared to normal skin." (PMID 26631117, 2015). "The purpose of this study was to: i) determine the mRNA amounts of IL-10, IL-10Rα, and IL-10Rβ in cutaneous and uveal melanoma cells and specimens; ii) evaluate their post-transcriptional regulation by miRNAs; iii) ascertain whether miRNA dysregulation may affect IL-10-induced proliferation." (PMID 26631117, 2015).
(Ss) (2 papers, 2016 to 2018). "To explore the association of Type III IFNs with Strongyloides stercoralis (Ss) infection, we examined the systemic levels of IFN lambda-1, IFN lambda-2 and IFN lambda-3, IL-10, and CXCL10/IP-10 in Ss infected (INF, n = 44), helminth—uninfected (UN, n = 44) and in post-treatment INF individuals." (PMID 30405603, 2018). "Thus, IL-10 and TGFβ play important roles in the antigen-induced expansion of Th9 cells in Ss infections." (PMID 26730582, 2016). "Thus, Ss infection is characterized by an IL-10- and TGFβ dependent expansion of Th9 cells, an expansion found to reversible by anti-helmintic treatment." (PMID 26730582, 2016).
Achilles tendinitis (2 papers, 2018 to 2020). "The intratendinous injection of DEX/PMSs into Achilles tendinitis rats both decreased the mRNA levels for these cytokines and increased mRNA levels for anti-inflammatory cytokines IL-4 and IL-10 in tendon tissues." (PMID 32090096, 2020). "In order to investigate the in vivo anti-inflammatory effects of SIM/PMSs on collagenase-induced Achilles tendinitis models, we monitored the mRNA levels of both pro-inflammatory cytokines (MMP-3, COX-2, IL-6, TNF-α, and MMP-13) and anti-inflammatory cytokines (IL-4, IL-10, and IL-13)." (PMID 29534523, 2018).
Acidosis (2 papers, 2022 to 2023). Abnormal acid accumulation or depletion of base. "However, respiratory acidosis in Protective Endogenous Hypercapnia caused an increase in BALF IL-10 concentrations, possibly exerting protective effects in distant organs." (PMID 35530505, 2022). "Acidosis did not significantly alter the frequency of IFN-γ-producing T cells, IL-4-producing T cells or IL-10-producing T cells ex vivo." (PMID 35708739, 2023).
acute leukemia (2 papers, 2012 to 2013). A clonal (malignant) hematopoietic disorder with an acute onset, affecting the bone marrow and the peripheral blood. "Nowadays, fewer studies propose to study polymorphisms in TNFα and IL10 genes in relation to prednisone glucocorticoid in acute leukemia during childhood." (PMID 23213548, 2012). "At the time of malignancy diagnosis, plasma from patients with acute leukemia displayed higher concentrations (P<0.05) of IL-6, IL-8, IL-10, and TNF-α and lower levels of pro-LL-37 (P<0.001)." (PMID 23741421, 2013). "The plasma from patients with acute leukemia displayed significantly higher concentrations of both pro-inflammatory cytokines (IL-6, IL-8, and TNF-α) and the anti-inflammatory cytokine (IL-10)." (PMID 23741421, 2013).
acute pharyngitis (2 papers, 2023 to 2025). An acute and painful inflammatory process that affects the pharynx. "In the experimental studies assessing the pharmacological effects of KHJ on acute pharyngitis before and after compatibility, all drug groups exhibited significant reductions in serum IL-1β, IL-6, and PGE2 levels, besides a notable increase in IL-10 levels." (PMID 41357871, 2025).
alcohol addiction (2 papers, 2022 to 2024). "Therefore, IL-10 can be used as a diagnostic indicator for alcohol addiction and can be applied in the treatment of alcohol addiction through the regulation of GABA release." (PMID 38898454, 2024).
alopecia (2 papers, 2024 to 2025). Hair loss usually from the scalp. "However, when IL-10 is blocked in these skin grafts, NKT cells are unable to prevent alopecia, indicating that their protective effect on hair loss is dependent on IL-10." (PMID 40959061, 2025).
alopecia areata (2 papers, 2021 to 2025). Loss of scalp and body hair involving microscopically inflammatory patchy areas. "In analyzing cytokine and vitamin levels, we observed that individuals with alopecia areata exhibited elevated average levels of IL-4, IL-10, TNF-α, and IFN-γ, surpassing those of healthy controls." (PMID 40352276, 2025). "In numerous studies, serum level of IL-10 in patients with alopecia areata was comparable with healthy controls; thus, further studies are needed to confirm the role of this cytokine in alopecia areata." (PMID 34943905, 2021). "In numerous of previously published studies, an increased serum level of IL-10 was described in patients with alopecia areata compared to healthy controls." (PMID 34943905, 2021). "IL-10 levels varied widely in both groups; however, the alopecia areata group indicated higher average levels (6.150 ± 16.510 pg/mL) compared to the control group (4.015 ± 6.267 pg/mL), though median values were similar at 1.525 pg/mL and 1.655 pg/mL, respectively." (PMID 40352276, 2025). "Expanding on this, our study examined a broader range of cytokines, including IL-2, IL-4, IL-6, IL-10, IFN-γ, and TNF-α, to evaluate their potential correlation with the onset and progression of alopecia areata in blood assays." (PMID 40352276, 2025). "While the blood analysis revealed higher average levels of IL-4, IL-10, and TNF-α in alopecia areata patients compared to healthy individuals, these differences were not statistically significant." (PMID 40352276, 2025). "Although the variations in cytokines and vitamins such as IL-2, IL-4, IL-6, IL-10, TNF-α, and vitamins in the blood are insufficient to differentiate alopecia areata, we have observed a notable increase in IFN-γ and decrease in IgG4 levels among patients with this condition." (PMID 40352276, 2025).
aortic aneurysm (2 papers, 2013 to 2020). A ruptured aneurysm located in the wall of the proximal portion of the descending aorta proceeding from the arch of the aorta. "The mRNA expressions of IFN-γ, IL-4 and IL-10 were significantly increased in the aortic aneurysms of Ang II-treated group compared with saline-treated controls." (PMID 24358274, 2013). "In addition to IL-6, IL-10 also played an important role in promoting the development of aortic aneurysm." (PMID 32509885, 2020).
arteriosclerosis (2 papers, 2016 to 2024). A vascular disorder characterized by thickening and hardening of the walls of the arteries. "Lymphocytes play a crucial role in the immune response and can secrete anti-inflammatory cytokines such as IL-10 to promote repair and protect against arteriosclerosis and brain damage." (PMID 39777309, 2024). "Since monocyte adhesion to endothelial cells plays a critical role in the pathogenesis of arteriosclerosis and restenosis, next we tested the effect of IL-10 on the binding of monocytes to the endothelial monolayer." (PMID 26808574, 2016).
Arthralgia (2 papers, 2022 to 2023). "Similarly, levels of IL-10 and INFγ were elevated in patients with arthralgia." (PMID 36408259, 2022). "ROC curve analysis yielded an optimal cut-off IL-2, IL-10, and INF-γ levels of 2.67, 5.93, and 5.32 pg/ml for the presence of arthralgia." (PMID 36408259, 2022).
astrocyte tumor (2 papers, 2014 to 2015). "Among subclasses of human astrocyte tumors, the most aggressive tumors contained the highest levels of IL-10 mRNA, with glioblastoma tissue containing the most of any astrocyte tumor." (PMID 26217588, 2015).
Atrophy (2 papers, 2021 to 2023). Any weakening or degeneration, especially through lack of use. "We demonstrate that IL-10 deficient mice exhibit significantly increased infarct sizes on days 3 and 7 and enlarged brain atrophy and impaired neurological outcome on day 14 following tMCAO." (PMID 34772416, 2021).
attention deficit-hyperactivity disorder (2 papers, 2020 to 2025). A disorder characterized by a marked pattern of inattention and/or hyperactivity-impulsivity that is inconsistent with developmental level and clearly interferes with functioning in at least two settings (e.g. at home and at school). "Nevertheless, both autism spectrum disorders (ASD) and attention deficit hyperactivity disorder (ADHD) are associated with increases in adaptive immune (T) cell cytokines, specifically Th2-like cytokines (IL-4, IL-6, and/or IL-10), or decreases in Th2-like cytokines (IL-2 and/or IFNγ)." (PMID 33424735, 2020). "In contrast, younger populations, such as children and adolescents, may show different cytokine profiles, with studies indicating elevated levels of IL-6 and IL-10 in children with attention-deficit/hyperactivity disorder (ADHD), which may overlap with depressive symptoms." (PMID 40305200, 2025).
autoimmune gastritis (2 papers, 2025). Inflammation of the body fundic mucosa of the stomach. "For example, the suppression of inflammatory disease of the colon requires the production of IL‐10 by Treg, while the milder inflammatory milieu of autoimmune gastritis can be suppressed by Treg in an IL‐10‐independent manner." (PMID 40346769, 2025).
Bartonella infection (2 papers, 2017). "However, anti-inflammatory effects of IL-10 have also been described in mild Bartonella infections where this cytokine would limit immunopathogenesis at the expense of allowing persistent infections." (PMID 28628613, 2017). "It is hypothesized that IL-10 induced immunosuppression is key in the development of severe Bartonellosis." (PMID 28628613, 2017). "Higher expression levels of IL-10 and IFN-γ were associated with current infections with Babesia and Bartonella, and cowpox virus, respectively, while lower expression levels of Gata3 were associated with cowpox virus infection and marginally associated with Babesia and Bartonella infection." (PMID 28817724, 2017).
beta-thalassaemia (2 papers, 2020 to 2022). "Our results of reduced IL-6, IL-10, and IL-8 serum levels in beta thalassemia disagree with findings of previous studies in this field, which are themselves controversial, probably due to differences in patient populations and therapies." (PMID 36699704, 2022). "In this study, we observed impaired production of IFN-gamma and IL-10 by whole blood from beta-thalassaemia patients upon stimulation with a range of bacteria-derived stimuli." (PMID 32581238, 2020). "Induction of HO-1 by hemin or CoPP in vitro reduced production of IFN-gamma and IL-10 from healthy human PBMCs and decreased bacterial clearance activity of whole blood from healthy controls and beta-thalassaemia, while inhibition of HO-1 by SnPP enhanced both functions in healthy controls." (PMID 32581238, 2020). "Likewise, we found that restimulation of whole blood from beta-thalassaemia/HbE patients with probable low-grade inflammation presented reduced IFN-γ and IL-10 production and bacterial killing activity which may lead to increased susceptibility to melioidosis." (PMID 32581238, 2020).
biliary atresia (2 papers, 2019 to 2021). A rare, biliary tract disease characterized by progressive obliterative cholangiopathy of the intra- and extrahepatic bile ducts, occurring in the embryonic/ perinatal period, leading to severe and persistent neonatal jaundice and acholic stool. "It is consistent with higher IL-2, IL-4, IL-6, IL-10, TNFα, and IFN-γ in patients with biliary atresia." (PMID 34630385, 2021).
Bladder Pain Syndrome (2 papers, 2021 to 2023). "Elevated urine IL-10 levels were noted in medically refractory DO patients with the potential to differentiate DO and interstitial cystitis." (PMID 37189809, 2023). "Interstitial Cystitis or Bladder Pain Syndrome (IC/BPS) is a heterogeneous condition characterized by elevated levels of inflammatory cytokines, IL-1β, IL-6, IL-8, IL-10, TNF-α, and is associated with debilitating symptoms of pelvic pain and frequent urination." (PMID 33923265, 2021).
Blastocystis infection (2 papers, 2014 to 2025). "Prior studies also noted probiotic benefits in IBD-related Blastocystis infections, with increased IL-10 and TGF-β levels." (PMID 41390811, 2025).
brain hemorrhages (2 papers, 2022). "PAI-2 deficiency increased C5a and reduced IL-10 concentration, resulting in increased mortality due to brain hemorrhages." (PMID 36309755, 2022).
bronchiolitis obliterans (2 papers, 2022 to 2024). "IL-10 gene therapy has been delivered using multiple vectors—such as adenovirus, lentivirus, and sendai virus—in chronic rejection models and has been shown to attenuate bronchiolitis obliterans (BO) following lung transplantation." (PMID 35844566, 2022). "In a mouse model of bronchiolitis obliterans, MSC infusion decreased IFN-γ level and increased IL-10 level in the serum." (PMID 39273184, 2024).